AURKA (aurora kinase A)
Diseases named in the same sentence as AURKA in open-access papers (continued):
Sharing a sentence is not in itself a finding about the gene and the disease.
neuroblastoma (continued). "Different aurora kinase inhibitors including the aurora kinase A inhibitors MLN8054 and alisertib (MLN8237), the aurora kinase B inhibitor AZD1152, and the pan aurora kinase inhibitor CCT137690 were demonstrated to display anti-neuroblastoma activity." (PMID 25268132, 2014). "Aurora kinase A expression and amplification were shown to be negative prognostic markers in neuroblastoma and to stabilise MYCN." (PMID 25268132, 2014). "Classifying MYCN non-amplified neuroblastomas into high and low groups, we demonstrated that the AURKA mRNA levels alone could predict the overall survival (HR 4.8; P < 0.0001)." (PMID 38553589, 2024). "Indeed, AURKA inhibitors, MLN8054 and MLN8237 (Alisertib), are able to disrupt this interaction, leading to N-MYC degradation and subsequently cell death and differentiation in neuroblastoma cells." (PMID 38553589, 2024). "MiR-186 in NK-Exos could down-regulate aurora A kinase (AURKA) and v-myc avian myelocytomatosis viral oncogene neuroblastoma-derived homolog (MYCN) expression, thereby suppressing cell proliferation and inducing apoptosis in neuroblastoma cells." (PMID 37543612, 2023). "Directly downregulates MYCN and AURKA in neuroblastoma cells, which can potentially have a negative impact on their survival; miR-186 upregulation in NK cells resulted in the downregulation of TGFBR1 and TGFBR2 and, thus, impaired the TGFβ1-dependent inhibition of NK cells’ cytotoxicity." (PMID 33530529, 2021). "Moreover, in neuroblastoma, stabilization of MYCN is a critical function of AURKA." (PMID 31920463, 2020). "Mitotic kinases, such as Aurora kinase A (AURKA) and Polo-like kinase 1 (PLK1), are reported to stabilize MYCN by inhibiting the Fbxw7-mediated degradation of the MYCN protein and may promote SCD in MYCN-amplified neuroblastoma cells." (PMID 33194665, 2020). "As with prostate cancer, AURKA has been linked to the disease but its inhibition does not alter MYCN levels, suggesting a difference in activity in MYCN-amplified non-small lung cancer cells (NSCLC) compared to MYCN-amplified neuroblastoma and prostate cancer." (PMID 28358317, 2017). "Small molecule inhibitors of AURKA, such as MLN8054 and MLN8237 (Alisertib), have been described to reduce MYCN stability by increased degradation, to increase survival in an in vivo model of neuroblastoma, and to reduce neuroblastoma-induced endothelial cell proliferation." (PMID 28358317, 2017). "AURKA stabilises MYCN via a direct interaction with a protein binding site flanking MYCN's MBI sequence, this stabilisation of MYCN exacerbates its oncogenic functions, and prevents differentiation of neuroblasts in MYCN-driven neuroblastoma (NB) cell lines, leading to aberrant proliferation." (PMID 34195095, 2021). "Although it is not yet known if this interaction contributes to neuroblastoma disease pathogenesis, it is intriguing that the interaction occurs at the promoter regions of several genes important for the development of neuroblastoma, including ALK, AURKA and BDNF." (PMID 21731748, 2011).
lung carcinoma (79 papers, 2005 to 2026). "In this study, we found that the highly prevalent KEAP1 deficiency sensitizes NSCLC cells to AURKA inhibitors, establishing AURKA as a potential therapeutic target in specific lung cancer." (PMID 38521813, 2024). "A variety of intracellular molecules are also DTP inducers in EGFR-mutated lung cancers, including Aurora kinase A, ERK, NF-kB, STAT3, and β-catenin." (PMID 37920509, 2023). "An increasing body of evidence suggests that FBP1, SBK1 and AURKA are associated with lung cancer progression." (PMID 37737707, 2023). "We here report that AURKA is amongst the strongest synthetic lethal candidate for RB1 deficiency in lung cancer cells." (PMID 33037191, 2020). "Here the authors perform chemical and genetic vulnerability screens and identify aurora A kinase (AURKA) as a synthetic lethal candidate for RB1-deficient lung cancer cells and that AURKA inhibition sensitizes these cells to mitotic cell death." (PMID 33037191, 2020). "We performed chemical and genetic vulnerability screens in RB1-isogenic lung cancer pair and herein report that aurora kinase A (AURKA) inhibition is synthetic lethal in RB1-deficient lung cancer." (PMID 33037191, 2020). "A first interesting observation about these genes is that many of them have been positively implicated in breast and/or lung cancer progression and resistance to therapy: AURKA, CAV2, RAB27A, RAD51, TIMELESS, TIMM17A." (PMID 22347440, 2012). "Accordingly, AURKA inhibition in RB1-deficient lung cancer is synthetically lethal." (PMID 39334449, 2024). "Finally, a prior publication showed that upregulation of the microtubule depolymerizing protein Stathmin 1 (STMN1) in RB1 deficient lung cancer cells created synthetic lethality with AURKA inhibition." (PMID 36372230, 2022). "Hence, our data indicate that high expression of AURKA in the nucleus is positively associated with RBM4 aberrant splicing in lung cancer." (PMID 35361747, 2022). "Furthermore, increased expression of AREG and AURKA in lung cancer cells has been associated with resistance to gefitinib treatment." (PMID 35216325, 2022). "Moreover, AK-01 has more potent anti-tumor activities in MCC-9 xenografts, which is consistent with the notion that AURKA inhibitor retained synthetic lethality in cancer cells with RB1 loss in lung cancers." (PMID 34359608, 2021). "In summary, by profiling EGFR phosphorylation in wild-type and mutant lung cancer cells, we identified a relationship between EGFR mutations and the phosphorylation of EGFR-Thr654 and -Ser1046, which was associated with AURKA expression in lung cancer patients and may be elicited by AURKA." (PMID 23520446, 2013). "Survival analysis revealed that overexpression of CDK1, PLK1, AURKA, KIFC1, and KIF2C was associated with a statistically significant unfavorable overall survival in patients with lung cancer." (PMID 40232858, 2025). "In some types of lung cancer, AURKA inhibitors in combination with EGFR inhibitors have been shown to provide greater tumor suppression than monotherapy." (PMID 39928563, 2025). "Nevertheless, YAP is a key downstream effector of AURKA and promotes proliferation and migration in lung cancer cells." (PMID 39334449, 2024). "Lung cancer cell lines resistant to cisplatin were reported to have a higher expression of AURKA and AURKA inhibition; in addition, cisplatin led to increased cytotoxicity in NSCLC cell lines." (PMID 39199578, 2024). "An example includes KCTD12, which is a mitotic target but upon overexpression in cervical and lung cancers promotes tumorigenesis in an AURKA-dependent manner." (PMID 39334449, 2024).
lung carcinoma (continued). "Relevant to this study, treatment of KRASG12C lung cancer cells with sotorasib has been shown to induce the increased expression of AURKA, which then directly interacted with KRASG12C, locking KRAS into an active, KRASG12C inhibitor–insensitive state." (PMID 38639476, 2024). "Our research into identifying new target genes for lung cancer therapy within the framework of external stimuli has brought to light two prominent candidates: AURKA downregulation and Cadherin 1 (CDH1) upregulation, also known as E-cadherin." (PMID 38707537, 2024). "According to proteomic sequencing analysis, AURKA, a classical cell cycle regulatory protein kinase, is highly expressed in NSCLC, and OP-B promotes ferroptosis in lung cancer in vitro and vivo by targeting AURKA." (PMID 37005430, 2023). "The ROC curves demonstrated good diagnostic efficacy for lung cancer, with AUC values of 0.962, 0.924, 0.886, and 0.95 for the four hub genes CENPF, AURKA, PBK, and CCNB1, respectively." (PMID 36984548, 2023). "AURKA has been well studied in multiple cancers, such as gastrointestinal, colorectal, breast, bladder, and lung cancers." (PMID 36984548, 2023). "Inhibition of AURKA expression reduced lung cancer cell growth and enhanced the sensitivity of lung cancer cells to radiation." (PMID 37737707, 2023). "miR449 overexpression in human lung carcinoma cells (H1299) was performed to prove AURKA regulation by miR449, and, indeed, the protein as well as the mRNA expression of AURKA was strongly reduced upon overexpression of miR449." (PMID 35887096, 2022). "At the same time, the HPA database was used to analyze the differences in the protein expression of AURKA in normal and lung cancer tissues." (PMID 35875069, 2022). "Together, our findings reveal that the m6A reader YTHDC1-directed RBM4 aberrant splicing is triggered by nuclear AURKA, providing novel opportunities for targeted therapy of lung cancer by blocking nuclear oncogenic signaling." (PMID 35361747, 2022). "The observation that HDAC inhibitors diminished AURKA expression in lung cancer cells supports the idea that AURKA transcription is regulated by epigenetic mechanisms." (PMID 36067794, 2022). "To further investigate the tumor-promoting mechanism of AURKA, we firstly examined the localization and expression of AURKA protein in lung cancer and adjacent normal tissues." (PMID 35361747, 2022). "To determine the role of AURKA in the regulation of RBM4 splicing in lung cancer cells, we utilized Doxycycline (DOX)-induced Tet-On-shAURKA to deplete the expression of endogenous AURKA." (PMID 35361747, 2022). "Previous studies have found that the repression of ubiquitin-conjugating enzyme E2O (UBE2O) or aurora kinase A (AURKA) can also promote radiation-induced DNA damage in lung cancer cells." (PMID 36139006, 2022). "Overexpression of AURKA is found in different cancers, including lung carcinomas, and is an established poor prognostic factor in lung, breast and colorectal cancers." (PMID 36387232, 2022). "Taken together, these data indicate that nuclear AURKA drives RBM4 RNA splicing switch from RBM4-FL to RBM4-S by a kinase-independent mechanism in lung cancer." (PMID 35361747, 2022). "Patients with higher expression of aurora kinase A showed significantly decreased OS compared with lower-expression patients in both lung cancer and adenocarcinoma." (PMID 35745617, 2022). "AURKA overexpression facilitates the migration and invasion of lung cancer cells and head and neck squamous cancer cells by activating Akt/FAK pathway." (PMID 35166647, 2022). "Overall, our results elucidate a novel mechanism of how nuclear AURKA regulates m6A reader YTHDC1-mediated RBM4 aberrant splicing, and provide therapeutic opportunities for lung cancer by targeting nuclear translocation of AURKA." (PMID 35361747, 2022). "Further functional characterization studies of AURKA report that AURKA suppression enhances the radiosensitivity of lung cancer and its response to EGFR inhibitors." (PMID 35520289, 2022).
lung carcinoma (continued). "In another genomic study of BM of various origin, several potentially actionable genomic alterations were associated with lung cancer BM, including AKT1, AURKA, CDK6, EGFR, MEK1, MET, and PIK3CA gene amplifications and CDKN2A deletions." (PMID 36561283, 2022). "Numerous studies have reported that AURKA was function as oncogenes to promote tumorigenesis in multiple types of cancer, including lung cancer, gastric cancer, and pancreatic cancer." (PMID 36050939, 2022). "In order to confirm a correlation between the expression levels of aurora kinase A and cancer survival, the clinical significance of aurora kinase A expression in patients with lung cancer and adenocarcinoma was analyzed using the Kaplan–Meier method." (PMID 35745617, 2022). "All three AURKA inhibitors showed strong antitumor effects on RB1−/− lung cancer xenografts in mice, while RB1+/+ tumors were much less sensitive to the inhibitors." (PMID 34050264, 2021). "Accordingly, the AURKs, in particular AURKA and B were proposed as promising targets for cancer therapy, e.g. in lung cancer treatment, where AURK inhibition is currently evaluated in clinical trials." (PMID 33829040, 2021). "CDC20 together with CENPA, CDK1, AURKA, and TPX2 were also diagnostic biomarkers in LUAD, and elevated mRNA levels of CDC20 were correlated with poor prognosis of lung cancer." (PMID 34650921, 2021). "Activation of AURKA is responsible for the resistance of lung cancer to third-generation EGFR inhibitors." (PMID 33451333, 2021). "Not only is the overregulation of AURKA in NSCLC patients was correlated with poorer overall survival and progression-free interval but was also implicated in cisplatin-resistance in lung cancer cells." (PMID 33202573, 2020). "We next tested AURKA inhibition in a panel of lung cancer cell lines with different RB1 status and found that the synthetic lethal effect appeared in general in RB1-mutant, SCLC cell lines." (PMID 33037191, 2020). "A current study has functionally characterized the AURKA inhibitor, TC-A2317, in human lung cancer cells." (PMID 33202573, 2020). "This study identified the hyper-vulnerability of RB1-deficient cells to AURKA inhibition, and mechanistically explored the synthetic lethal crosstalk between RB1 and AURKA pathways in lung cancer cells." (PMID 33037191, 2020). "This study provides strong evidences to support the model that AURKA inhibition promotes the stathmin activity, resulting in the disruption of microtubule dynamics, which sensitizes RB1-deficient lung cancer cells to mitotic cell death." (PMID 33037191, 2020). "A Phase 1/1b clinical trial of AURKA inhibitor Alisertib with osimertinib in metastatic EGFR-mutant lung cancer is currently recruiting participants (NCT04085315)." (PMID 32292420, 2020). "Kaplan–Meier curves demonstrated that lung cancer patients with high level of AURKA had significantly poorer survival." (PMID 27713168, 2016). "We aimed to determine the short- and long-term effect of pharmacological inhibition of Aurora kinase A activity on the survival of lung cancer cells." (PMID 27713168, 2016). "Many of these aberrations were specific to the primary tissue of origin of the cancer, for example, lung developmental transcription factor NKX2-1 in lung cancer, AURKA in colon cancer and AR in prostate cancer." (PMID 25889064, 2015). "Over-expression of AURKA has been detected in many tumor cells and tissues, such as breast, gastric, colorectal, bladder, pancreatic, ovarian, prostate and lung cancers." (PMID 21718475, 2011). "Thus, elucidating the role of AURKA in lung cancer and examining the gene and cellular functions it regulates are crucial for assessing its therapeutic potential." (PMID 40564876, 2025).
lung carcinoma (continued). "In addition, Aurora kinase A and B inhibition is synthetically lethal in combination with RB1 loss in breast and lung cancer cells." (PMID 38837893, 2024). "AURKA levels positively correlate with YAP levels in lung cancer." (PMID 39334449, 2024). "Relevant bioinformatics analysis suggests AURKA may be a key gene in lung cancer, which could lead to poor prognosis." (PMID 38794152, 2024). "In addition, AURKA has been reported to be involved in the resistance of third-generation tyrosine kinase inhibitors in lung cancer patients." (PMID 37072406, 2023). "High expression of AURKA correlated with shorter OS in lung cancer patients." (PMID 37737707, 2023). "The relevance of AURKA in lung cancer patients is stressed by the correlation of poor outcomes with AURKA expression, which could also be correlated to resistance toward the KRASG12C inhibitor in vitro." (PMID 35565305, 2022). "AURKA is overexpressed in poorly differentiated lung cancer cells." (PMID 36101460, 2022). "Furthermore, previous studies have suggested that tRF-Leu-CAG affected the proliferation of lung carcinoma cells by targeting the Aurora Kinase A (AURKA) protein, which participated in the control of cell cycle and the regulation of the cell division." (PMID 35574338, 2022). "CBLC could delay the accumulation and activation of AURKA through consumption to prevent cancer cells from entering cell division and increase the apoptosis of lung cancer cells." (PMID 36339610, 2022). "In fact, what was achieved from our result was that the expression level of AURKA could be upregulated in stomach, colorectal, liver, ovarian, bladder, prostate, head and neck, lung, kidney, and lung cancers." (PMID 34337875, 2021). "Moreover, it has been reported that AURKA drives the evolution of resistance to EGFR inhibitors in lung cancer, and the aberrant activation of AURKA contributes to the highly aggressive nature of lymphoproliferative disorders." (PMID 34359608, 2021). "Both AURKA and AURKB have been implicated in the development of lung cancer growth." (PMID 33202573, 2020). "In NCSLC, overexpression of AURKA and AURKB has been associated with poor prognosis due to reduced overall survival and both kinases have been found to either potentiate or repress chemo- and/or radiotherapy in lung cancer." (PMID 33202573, 2020). "An investigational topoisomerase inhibitor, daurinol, in combination with radiation could effectively decrease lung cancer growth in xenograft mouse models through the inhibition of AURKA and AURKB." (PMID 33202573, 2020). "However, the utility of AURKA inhibitors in EGFR mutant lung cancer exceeds this specific molecular context." (PMID 32292420, 2020). "Furthermore, Survivin/BIRC5 interacted closely with molecules which were shown to regulate stem cell properties in lung adenocarcinomas (SPC25), influence radiosensitivity in lung cancer (AURKA), or mediate anti-EGFR therapy in NSCLC (AURKB)." (PMID 32039023, 2019). "Furthermore, targeting Aurora kinases by RNA interference reduces the oncogenic phenotype of KRAS mutant lung cancer cells in vitro and AURKA targeting slows tumor growth in vivo." (PMID 26842935, 2016). "Interestingly, AURKA and AURKB expression levels have been used as diagnostic and prognostic markers in lung cancer, suggesting that these kinases play a role in lung oncogenesis." (PMID 26842935, 2016). "The interplay between EGFR and AURKA provides an explanation for the difference in EGF dependency between EGFR-WT and EGFR-mutant cells and may provide a new therapeutic strategy for lung cancer patients carrying EGFR mutations." (PMID 23520446, 2013). "To test the hypothesis of a similar mechanism in lung cancer we evaluated the effect of AURKA inhibition in NSCLC cell lines (H522, H1299 and Calu1)." (PMID 21718475, 2011).